CD163 (CD163 molecule)
Diseases named in the same sentence as CD163 in open-access papers (continued):
Sharing a sentence is not in itself a finding about the gene and the disease.
COVID-19 (continued). "The study aimed to investigate the role of soluble (s)CD163 and sCD14 plasmatic levels in predicting disease severity and characterize peripheral blood monocytes and dendritic cells (DCs), in patients with COVID-19 pneumonia (COVID-19 subjects)." (PMID 33777012, 2021). "A higher frequency of CD163+ CD14+ cells in the DC3 subpopulation correlated with systemic inflammation suggesting that these cells may play a role in inflammatory responses of COVID-19 patients." (PMID 34614036, 2021). "Integrated multi-omics analyses of COVID-19-associated Rapid pulmonary fibrosis (RPF) patients and murine models reveal that CD163+ macrophages drive rapid pulmonary fibrosis progression via SPP1 secretion, identifying the CD163+-SPP1 axis as a potential therapeutic target." (PMID 41293726, 2025). "These elevated systemic sCD14 levels detected in patients with anxiety were consistent with high systemic CD163 levels (another marker of monocyte activation) found in the bloodstream of COVID-19-infected patients, which could enhance monocyte–macrophage mobilization." (PMID 39334711, 2024). "In the acute hyperinflammatory phase, distinct subsets of monocyte-like cells (CD163+SLC39A8+CALR+ infMonos) and Tinf cells (MX1+IRF1+ISG15+) emerged, a phenomenon also observed in patients with sepsis and COVID-19." (PMID 40251340, 2025). "Other work demonstrating infection of lung macrophages in SARS-CoV-2 patients has found that CD163 + LGMN+ exposed to SARS-COV-2 promote fibrosis and Acute Respiratory Distress Syndrome (ARDS) in COVID-19." (PMID 40674406, 2025). "Determine the cellular character of the inflammatory infiltrate in children of different age groups with COVID-19 based on the levels of expression of immunocompetent cell differentiation clusters: CD3, CD4, CD20, CD68, CD163, and CD138." (PMID 38397914, 2024). "Ceramides exhibited positive correlations with markers of macrophage activation (CD163 and CD206) that typically increase during the innate immune response in COVID-19 patients." (PMID 38540716, 2024). "In addition, double immune fluorescence staining for CD163 (red fluorescence) and PD-L1 (green fluorescence, marked by white arrows) showed that maternal M2 polarized macrophages are localized in close vicinity to PD-L1 positive EVTs in post-COVID-19 placentas." (PMID 39589546, 2024). "We have recently reported the potential profibrotic mechanism in COVID-19 by studying heat shock protein (HSP)-47+ myofibroblasts and CD163+ macrophages markers in explanted hearts from autopsied patients." (PMID 38535768, 2024). "An increase in CD3+, CD4+, CD68+, CD163+, and CD20+ CD138+ immunocompetent cells was found in the appendix of children with COVID-19." (PMID 38397914, 2024). "We next tested whether the proportion of CD163/LGMN Macrophages was associated with decreased ventilator-free days, given that this subset has recently been associated with a “pro-fibrotic” phenotype in patients with severe COVID-19 or idiopathic pulmonary fibrosis." (PMID 37978185, 2023). "CD163+ macrophages are of monocyte origin and accumulate in pulmonary infiltrates in the ARDS of COVID-19, demonstrating a profibrotic M2 transcriptional phenotype." (PMID 37109672, 2023). "In this study, the expression of macrophage markers (CD68 and CD163), ACE2, and caspase-3 was investigated based on the results of two fatal clinical observations of COVID-19." (PMID 37109672, 2023). "As for CD163, the mean of controls was 9.6 positive cells/HPF, while the mean of COVID-19 patients was 41.4 (p = 0.0029)." (PMID 35326463, 2022). "Here, we report the interesting role of TMPRSS2, CD45-, CD163/CD206, and CD33 in COVID-19 aggressiveness." (PMID 36969980, 2022). "Significant positive correlations were found between serum levels of soluble CD25 and CD163 in all patients with SARS-CoV-2 (r = 0.445, P = 0.016) and patients with COVID-19 (r = 0.662, P = 0.014)." (PMID 35233677, 2022).
COVID-19 (continued). "This analysis indicates the relevant role of several markers such as TMPRSS2, CD45-, CD163/CD206, and CD33 for COVID-19 aggressiveness." (PMID 36969980, 2022). "The hallmarks of severe COVID-19 forms are decreased levels of HLA-DR and CD86, as well as increased levels of CD163 in all subsets of circulating monocytes." (PMID 35632823, 2022). "CD163 and TREM-1 levels were relatively low in both viral CAP groups (CAP-flu and COVID-19), although only significant in the latter group." (PMID 35660785, 2022). "Even after random sampling analysis, CD163 and CD61 protein expression remained significantly higher in COVID-19 patients." (PMID 35260724, 2022). "CD163 and CD61 staining were used to examine the inflammatory and coagulopathy components of COVID-19." (PMID 35260724, 2022). "Higher expression of CD163 was detected in monocytes and DC3 of COVID-19 patients with severe disease." (PMID 34614036, 2021). "An increased fraction of a putative M2-polarized phenotype, as exemplified by an increase of CD163+ (and CD206+) cells in the lymph nodes, was similarly observed in lung samples of COVID-19 patients." (PMID 34966385, 2021). "CD163 has been reported to be increased in hospitalized COVID-19 patients compared to non-hospitalized COVID-19 individuals and healthy controls." (PMID 41369364, 2025). "In accord with a previous study that reported dysregulated and immature CD163high and HLA-DRlow blood monocytes in severe COVID-19 but not in healthy controls, we found elevated CD163 and lower HLA-DR on the surface of monocytes in our study." (PMID 40710346, 2025). "Finally, immunohistochemistry validated the accumulation of both CD163+ macrophages and CD80+ proinflammatory macrophages in pancreatic tissues of COVID-19 patients." (PMID 39232561, 2024). "Another striking finding was that we identified PD-L1 positive maternal macrophages (CD163-positve) in the acute COVID-19 male decidua; this upregulation (although not significant) was also found in the post-COVID-19 situation but only in male placentas." (PMID 39589546, 2024). "Diagnostic criteria such as HScore or HLH-2004 may have suboptimal performance in identifying COVID-19 HLH-like presentations, and criteria such as soluble CD163, NK cell activity, or other novel biomarkers may be more useful in identifying this entity." (PMID 33803997, 2021). "For example, the concentrations of MIP-1α/CCL3, soluble CD163 (sCD163), and M-CSF were elevated in all COVID-19 patients compared with HVs, regardless of severity." (PMID 33232303, 2021). "Additionally, a smaller number of biopsies (COVID-19 n = 5, controls n = 6) were analyzed for the expression of ACE2 and TMPRSS2 as mediators of virus entry as well as for the expression of EpCAM, CD8α, CD31, and CD163." (PMID 34420043, 2021). "In a total of 55, 44 COVID-19 post-mortem lung samples were tested for ACE2, 36 for CD163, and 26 for CD61, compared to 15 non-covid 19 control lung sections." (PMID 35260724, 2022). "Similarly, a clustering pattern of acute-phase COVID-19 non-classical monocytes upon bacterial challenge was characterized by an increased expression of CCR2, CD163 CD120b, CD11b and low expression of HLA-DR." (PMID 35007290, 2022). "Notably, both COVID-19 skin phenotypes—but not CLE—showed a marked upregulation of genes related to macrophage function, including macrophage receptors (CD209, CLU, MARCO, FCGR2A, CLEC5A, CD163, MRC1 and BST1), differentiation factors (IL32) and monocyte-recruiting chemokines (CXCL2 and CCL2)." (PMID 35045565, 2022).
Sepsis (81 papers, 2007 to 2026). Sepsis is defined as life-threatening organ dysfunction caused by a dysregulated host response to infection. "This analysis underscores the importance of multiple immunomodulatory proteins, particularly CD27, KLRB1, RETN, and CD163, in the risk of clinically overt sepsis, suggesting their potential as candidates for disease prognosis and treatment targets." (PMID 41472734, 2025). "Survival analysis revealed significant associations of KLRB1, RETN, and CD163 with sepsis prognosis." (PMID 41472734, 2025). "Macrophage activation is an important part of the etiology of several diseases, and serum CD163 levels are associated with obesity, sepsis, insulin resistance, diabetes, NASH, and portal hypertension." (PMID 37165352, 2023). "The authors linked the increase in IL-18 and CD163 concentrations to two sepsis-associated phases: early pro-inflammatory and late, anti-inflammatory, respectively." (PMID 36767629, 2023). "Macrophages in secondary lymphoid organs are likely to be important for clearing apoptotic lymphocytes in sepsis and for expressing M2-associated markers CD163 and CD206." (PMID 30866434, 2019). "The upregulation of CD163 at the occurrence of sepsis, caused by activating the waterfall effect from the secretion of anti-inflammatory cytokines, helps scavenge hemoglobin and reduce its oxidative impairment to the body." (PMID 23935252, 2013). "This study aimed to investigate the diagnostic value of urine soluble CD163 (sCD163) for identification of sepsis, severity of sepsis, and for secondary AKI, and to assess the patients’ prognosis." (PMID 23013330, 2012). "Interestingly, RETN and CD163 were positively correlated with the risk of sepsis-related death, whereas KLRB1 was negatively correlated with this risk." (PMID 41472734, 2025). "One study involving patients with sepsis and features of HLH showed that soluble CD163 (sCD163) could serve as a differential biomarker for sepsis-associated HLH versus sepsis." (PMID 37653176, 2023). "For example, CD163, which is abundant in the walls of IAs (but typically associated with macrophages), has been shown to be increased in neutrophils during sepsis and thus could be contributing to vascular inflammation in IA." (PMID 30593281, 2018). "Furthermore, we determined if the modulation of monocytes’ function during sepsis is associated with the phenotype of cells expressing CD163." (PMID 26879814, 2016). "Notably, the expression levels of KLRB1, RETN, and CD163 are closely linked to patient prognosis and may serve as potential targets for future sepsis immunotherapy." (PMID 41472734, 2025). "Based on an in-depth analysis of pediatric sepsis cohort data, this study is the first to identify a potential regulatory role the CD163 gene in pediatric septic shock progression." (PMID 40599778, 2025). "Monocytes that were CD206- and CD163+ were present in higher proportion in patients with sepsis (p=0.01)." (PMID 39935482, 2025). "We concluded that the early increase of CD163+ induced by iron overload during sepsis-induced collagen deposition would progress the AKI to chronic kidney disease within this timeline." (PMID 39949667, 2025). "The admission value of CD163 has a significant impact on the prediction of mortality in sepsis patients." (PMID 40599778, 2025). "In conclusion, our research revealed that CD27, KLRB1, RETN, and CD163 are highly specific and sensitive biomarkers for sepsis." (PMID 41472734, 2025). "used CD163 as an important functional marker in their studies on the distribution and inflammatory phenotype of circulating monocyte subsets in patients with sepsis." (PMID 40599778, 2025). "We identified and validated CD27, KLRB1, RETN, and CD163 as key biomarkers of sepsis by integrating transcriptome and single-cell data using bioinformatics and machine learning." (PMID 41472734, 2025). "Our study provides a theoretical basis for CD14 and CD163 as new biomarkers for predicting sepsis in children." (PMID 40626122, 2024).
Sepsis (continued). "DEX treatment counteracted TNFα and LPS downregulation of CD163 and even increased expression above baseline for both treatments, which will be beneficial for both moderate and severe sepsis." (PMID 39619227, 2023). "Another study discovered that haptoglobin also bound HMGB1 through a CD163-dependent pathway that confers protection against HMGB1-mediated inflammation in sepsis." (PMID 36230933, 2022). "They reported a more robust increase in EV-CD163 in patients with sepsis than a more substantial increase in ectodomain CD163 in exposure to endotoxin; thus, the authors recommend continued research to differentiate the two." (PMID 33498620, 2021). "The anti-inflammatory phenotypes, including CD206 and CD163, were also evaluated and showed significant increases under persistent sepsis exposure." (PMID 34512319, 2021). "The authors of this study concluded that there should be a recognized designation between EV-CD163 and ectodomain CD163, as they noted differential distributions of serum-soluble CD163 in sepsis cases and exposures to endotoxin." (PMID 33498620, 2021). "We further evaluated the expressions of CD206 and CD163 and found that both molecules showed significantly upregulated expressions at 48 h post sepsis induction." (PMID 34512319, 2021). "Soluble CD163 (sCD163) is an important biomarker in various inflammatory diseases including sepsis, liver disease, and macrophage activation syndrome." (PMID 32824692, 2020). "In this case, differences between CD163+ and CD163− cells were only observed in septic patients; under both bacterial stimuli, ROS generation was higher in sepsis patients than in healthy volunteers for both CD163+ and CD163− monocytes." (PMID 26879814, 2016). "Although membrane and soluble forms of CD163 share the ability to be biomarkers of prognosis in sepsis, circulating CD163 reflecting the polarization of monocytes or their activation independently of M1/M2 polarization tends to be ignored." (PMID 25346736, 2014). "Soluble forms of M2-type markers such as CD163 and CD206 are also increased in patients with sepsis, and their high levels are associated with poor prognosis in sepsis." (PMID 25346736, 2014). "In the current study, urine CD163 concentrations were abnormally increased during sepsis, with urine sCD163 concentrations in the sepsis group significantly higher than those in the SIRS group." (PMID 23013330, 2012). "In patients with sepsis, the percentages of cells expressing CD163 was higher in CD14++CD16− (median: 29.6%) and CD14++CD16+ (median: 27.00%) subsets than in the CD14+CD16+ subset (median: 0.00%)." (PMID 22693573, 2012). "The increased expression of CD206 and CD163 on circulating monocytes in our study supports the conclusion that alternative activation of monocytes occurs during sepsis." (PMID 22693573, 2012). "We investigated serum soluble CD163 (sCD163) levels for use in the diagnosis, severity assessment, and prognosis of sepsis in the critical ill patients and compared sCD163 with other infection-related variables." (PMID 22911680, 2012). "We found a dramatic increase in the percentage of monocytes expressing CD206 and CD163, indicating the alternative activation of monocytes, which supports previous studies showing a reprogramming of monocyte function during sepsis." (PMID 22693573, 2012). "Only one author found increased bone marrow infiltrationwith CD163-positive macrophages in postmortem analysis of samples from patientswho died from severe sepsis or septic shock compared with controls." (PMID 18604302, 2008). "Based on this study’s findings and existing research theories, we propose that CD27, KLRB1, RETN, and CD163 may collaboratively regulate immune homeostasis in sepsis through their interactions." (PMID 41472734, 2025). "Thus, CD163’s role is highly microenvironment-dependent, potentially offering both protective and pathological effects in sepsis." (PMID 41472734, 2025).
Sepsis (continued). "During sepsis, changes in CD163 expression reveal the polarization state of macrophages." (PMID 41472734, 2025). "Enzyme-linked immunosorbent assay (ELISA) was used to detect serum of sepsis patients admitted to ICU on different days (1 day, 3 days, 5 days), and the results showed that septic shock was associated with the highest concentration of CD163." (PMID 40599778, 2025). "Very little is known regarding the role of CD163+ monocytes and macrophages in sepsis." (PMID 35741108, 2022). "The ASC-mediated increase of CD206, CD209, and CD163 on the surface of Mphs and mDCs suggests an enhanced ability to clear a range of blood-borne pathogens, supporting a therapeutic potential in infection-mediated diseases such as sepsis." (PMID 33138862, 2020). "Moreover, IsdB-immunized CD163–/– mice are resistant to sepsis following S. aureus SSI, as are normal healthy mice given anti-CD163–neutralizing antibodies." (PMID 33004694, 2020). "Our data also suggest that disruption of multimolecular complex formation and/or CD163 blockade may be approaches to prevent sepsis following SSI." (PMID 33004694, 2020). "As TWEAK activates by binding Fn14 receptor and is scavenged by binding the monocyte/macrophage scavenger receptor CD163, future studies focusing on the dynamic changes of Fn14 and CD163 in sepsis are required to reveal how the inflammatory response develops during the course of disease." (PMID 30733876, 2019). "Future inquires focusing on the alternations of Fn14 and CD163 may be helpful to reveal the diverse inflammatory response and immune state at different stages of sepsis." (PMID 30733876, 2019). "Elevated levels of soluble and monocyte CD163 expression have also been reported in acute-on-chronic liver failure, and may be predictive of hospital patient mortality in patients with sepsis." (PMID 27309850, 2016). "In patients with sepsis, the percentage of monocytes expressing CD163 and CD206 is increased." (PMID 25346736, 2014). "There was also a strong correlation between renal tissue iron overload with iNOS upregulation iNOs/Arg1 ratio, CD8+, CD68+, and CD163+ macrophage phenotype, indicating the impacts of both iron overload and inflammatory macrophages on each other within 72 h of induction of sepsis." (PMID 39949667, 2025). "Thus, diabetic patients with sepsis are more likely to activate the anti-inflammatory CD163." (PMID 36687421, 2022). "In others reports, the expression of CD163 by monocytes is accurate for discriminating patients with inflammatory presentation from those with sepsis, suggesting that CD163 may be a biomarker of prognosis and that the expression of CD163 by monocytes is higher in non-survivors than in survivors." (PMID 25346736, 2014). "In this study, three core genes (CD163, MCEMP1 and RETN) that lead to sepsis death in children were screened out, providing a new understanding of the lethal mechanism of sepsis in children and a promising new therapeutic approach." (PMID 40599778, 2025). "Based on single-cell transcriptome sequencing of PBMCs from controls and septic patients, NEAT1+ CD163+, and CD16+ monocyte clusters were identified as highly correlated with clinical indicators of sepsis." (PMID 37919720, 2023). "Here we identify a unique subpopulation of cardiac-resident macrophages termed CD163+RETNLA+ (Mac1), which undergoes self-renewal during sepsis and can be targeted to prevent SICM." (PMID 36635449, 2023). "Decreased percentages of CD163+CD14+ monocytes and increased monocytic CD163 were observed in type 2 diabetes and obesity, as well as in sepsis patients." (PMID 36687421, 2022). "Two cases in which sepsis or significant infection was documented (cases 22 and 8) had mean CD45, CD68 and CD163 counts of 19.3, 27.4 and 34.1 cells/mm, respectively." (PMID 24402186, 2014). "Two cases in which sepsis or significant infection was documented had mean CD45, CD68 and CD163 counts of 31.8, 28 and 33 cells/mm, respectively." (PMID 24402186, 2014).